FLRT1 (fibronectin leucine rich transmembrane protein 1)
Description:
Plays a role in fibroblast growth factor-mediated signaling cascades that lead to the activation of MAP kinases. Promotes neurite outgrowth via FGFR1-mediated activation of downstream MAP kinases. Promotes an increase both in neurite number and in neurite length. May play a role in cell-cell adhesion and cell guidance via its interaction with ADGRL1/LPHN1 and ADGRL3.
Synonyms: MGC21624; SPG68
Tractability: Small molecule: it belongs to a druggable protein family. Antibody: its Gene Ontology location is reachable by antibodies, with high confidence; UniProt places it where antibodies can reach, with medium confidence; UniProt predicts a signal peptide or a membrane-spanning region.
Gene: Protein-coding gene on chromosome 11 (64,035,931 to 64,119,173, forward strand). Ensembl gene ENSG00000126500.
Subcellular location: Cell membrane; Endoplasmic reticulum membrane; Cytoplasmic vesicle membrane; Cytoplasm, perinuclear region; Cell junction, focal adhesion; Secreted; Cell projection, neuron projection; Cell junction
Pathways (Reactome):
Signal Transduction: Downstream signaling of activated FGFR1
Gene Ontology:
Molecular function: protein-macromolecule adaptor activity; fibroblast growth factor receptor binding
Biological process: dendrite development; fibroblast growth factor receptor signaling pathway; neuron projection extension
Cellular component: anchoring junction; cell-cell junction; cytoplasmic vesicle; cytoplasmic vesicle membrane; endoplasmic reticulum membrane; extracellular matrix; extracellular region; focal adhesion; neuron projection terminus; neuronal cell body membrane; perinuclear region of cytoplasm; plasma membrane; neuron projection
Genetic constraint (gnomAD): Loss-of-function variants: 14 observed, 32.1 expected, observed/expected ratio (o/e) 0.44, 90% interval 0.29 to 0.68. The upper end of that interval is the gene's LOEUF score, 0.68, which puts it in group 2 of 6, group 1 being the genes least tolerant of losing a copy. Missense variants: 737 observed, 980.95 expected, observed/expected ratio (o/e) 0.75, 90% interval 0.71 to 0.8. Synonymous variants: 368 observed, 445.25 expected, observed/expected ratio (o/e) 0.83, 90% interval 0.76 to 0.9.
Homologues: Orthologues: chimpanzee FLRT1 (99% identical), macaque FLRT1 (99% identical), guinea pig FLRT1 (97% identical), rat Flrt1 (97% identical), dog FLRT1 (97% identical), mouse Flrt1 (96% identical), pig FLRT1 (95% identical), rabbit FLRT1 (95% identical), tropical clawed frog flrt1 (84% identical), zebrafish flrt1b (58% identical). Paralogues in human: FLRT3 (56% identical), FLRT2 (41% identical), LRRC4C (20% identical), LRRC4B (20% identical), LRRC15 (19% identical), LRRC4 (19% identical), PODN (17% identical), GP1BA (16% identical), LRRTM3 (16% identical), LRRTM4 (16% identical), PODNL1 (16% identical), LRRC66 (16% identical), and 10 more.
Diseases named in the same sentence as FLRT1 in open-access papers:
FLRT1 is named in the same sentence as 6 diseases in open-access papers, as found by Europe PMC text mining. Sharing a sentence is not in itself a finding about the gene and the disease. The quoted sentences say what the papers report.
Lissencephaly (2 papers, 2019 to 2025). A spectrum of malformations of cortical development caused by insufficient neuronal migration that subsumes the terms agyria, pachygyria and subcortical band heterotopia. "Notably, the only two other genes known to maintain lissencephaly in the mouse (or any other lissencephalic species) are Flrt1 and Flrt3 which redundantly regulate neuronal adhesion during migration." (PMID 31729356, 2019).
gastric cancer (1 paper, 2023). A primary or metastatic malignant neoplasm involving the stomach. "These analyses showed 15 genes were implicated in the prognosis of gastric cancer, including AC011374.1, AC018781.1, ADAMTS9-AS1, AL139002.1, AL391152.1, HOTTIP, FLRT1, NKX2-1-AS1, ADAMTS9-AS2, LINC00326, VCAN-AS1, SERPINE1, POU6F2-AS2, IGF2-AS, and miR-145." (PMID 37696973, 2023).
glioma (1 paper, 2010). A benign or malignant brain and spinal cord tumor that arises from glial cells (astrocytes, oligodendrocytes, ependymal cells). "Among these, CDH13, TIAM1 and PCDH17 were up- and FLRT1 and OPCML down-regulated, thus indicating that the invasion capacity of glioma cells can be altered by cisplatin treatment." (PMID 21637621, 2010).
neuroblastoma (1 paper, 2010). Neuroblastoma (NB) is the most common solid, extracranial childhood tumor. "Functional investigation of FGFR1 and FLRT1 signalling in SH-SY5Y neuroblastoma cells reveals that FLRT1 alone acts to induce a multi-polar phenotype whereas the combination of FLRT1 and FGFR activation, or expression of Y3F-FLRT1, acts to induce neurite outgrowth via MAPK activation." (PMID 20421966, 2010).
psoriasis (1 paper, 2024). An autoimmune condition characterized by red, well-delineated plaques with silvery scales that are usually on the extensor surfaces and scalp. "For WHRadjBMI and psoriasis, the most significant shared SNP (rs56348466, pCAPSSOC=2.09×10-8) was near MACROD1 and FLRT1." (PMID 38550599, 2024).
FLRT1 also shares sentences with these, for which no sentence is quoted: cancer (2 papers).